RN7SL647P (RNA, 7SL, cytoplasmic 647, pseudogene)
Gene: Miscellaneous RNA gene on chromosome 3 (78,115,158 to 78,115,457, forward strand). Ensembl gene ENSG00000243957.
Homologues: Orthologues: chimpanzee Metazoa_SRP (97% identical). Paralogues in human: RN7SL126P (78% identical), RN7SL357P (78% identical), RN7SL1 (78% identical), RN7SL2 (77% identical), RN7SL3 (77% identical), RN7SL296P (77% identical), RN7SL797P (76% identical), RN7SL45P (76% identical), RN7SL164P (76% identical), RN7SL341P (76% identical), RN7SL378P (76% identical), RN7SL664P (76% identical), and 701 more.